IL15 (interleukin 15)
Diseases named in the same sentence as IL15 in open-access papers (continued):
Sharing a sentence is not in itself a finding about the gene and the disease.
tumor (continued). "Thus, the most novel finding in our studies was that when IL-15 complexes were delivered via the intratumoral route, the cytokine reached the tumor-draining lymph nodes, activating CD8+ T cells and other immune cells and inducing their migration into the TME." (PMID 41373645, 2025). "Within the draining tumor lymph node, anti-PD-1 mAb and IL-15 complexes colocalize." (PMID 41373645, 2025). "Especially the intra-tumor injection or inhalation of a human cytokine (IL-2, IL-12, IL-15) could be an attractive treatment option for certain canine cancers with minimal side effects and the possibility of inducing a vaccine-like effect." (PMID 40671820, 2025). "Similarly, IL-15 signaling, which decreases mTORC1 activity, is associated with metabolic changes in CAR-T cells that can improve anti-tumor activity by preserving their stem cell memory phenotype." (PMID 39965008, 2025). "Furthermore, the effects of IL-15 appear to be highly context dependent, varying with the immune cell type, tumor microenvironment, route of administration, and vector design." (PMID 40564987, 2025). "In a mouse anti-cancer study, Pembrolizumab-IL-15Rα-IL15 (3 mg kg-1) exhibited slightly improved tumor-growth inhibition, reducing tumor size by 94% compared to commercial Pembrolizumab (5 mg kg-1) with an 83% reduction, regardless of statistically significant difference." (PMID 39808627, 2025). "Moreover, identifying biomarkers that predict which patients or tumor types are exceptionally responsive to IL-15 superagonist immunotherapy will aid this clinical development." (PMID 41373645, 2025). "Consistently, expression of IL-15 resulted in blockade of tumor progression in the TKP CCA model." (PMID 41332325, 2025). "Using conventional fluorescent and light-sheet fluorescent microscopy, we show that two doses of intratumoral IL-15 complexes coupled with anti-PD-1 mAb reach the tumor-draining lymph node, where they can engage CD8+ T cells and other immune cells, resulting in their activation." (PMID 41373645, 2025). "Based on their localisation, Il12b cDC1s might be important to sustain TCF1+ T cells at the tumour border, potentially through local expression of IL‐12, IL‐15 trans‐presentation and/or antigen (cross‐) presentation." (PMID 40745918, 2025). "Additionally, cytokine therapies, including IL‐2, IL‐7, IL‐12, and IL‐15, are being explored to rejuvenate T cells and boost anti‐tumor responses." (PMID 40178455, 2025). "We further speculate that TME disruption by CAR-T cells may dismantle the tumor-stromal barrier, facilitating improved infiltration of IL-15 and effector cells and resulting in a synergistic therapeutic effect." (PMID 41455698, 2025). "Overexpression of IL15 may promote tumor development through various pathways, stimulating cancer cell proliferation, inhibiting cell apoptosis, and affecting the immune microenvironment." (PMID 40070829, 2025). "However, this approach has not effectively addressed the challenge of achieving sufficient IL-15 infiltration within the tumor microenvironment." (PMID 41455698, 2025). "Trispecific antibodies that include IL-15 have demonstrated the ability to enhance natural killer and T-cell proliferation, while tumor-localized IL-2 delivery helps activate immune cells directly at the tumor site with minimal systemic side effects." (PMID 39982231, 2025). "Notably, CAR19 CIML NK cells co-expressing IL-15 have demonstrated improved tumor clearance and prolonged survival in lymphoma models." (PMID 40498022, 2025). "However, IL-2 and IL-15 can be utilized by inhibitory cells including tumor-infiltrating regulatory T cells, which are known to suppress the anti-tumor function of infused CAR T cells." (PMID 40808942, 2025). "Blocking EGFR might reshape the tumor microenvironment, enhancing NK cell function through cytokine release (e.g., IL-12, IL-15) and interferon-gamma." (PMID 40869384, 2025). "Examples include the delivery of L-methioninase, tumor antigens and IL-15." (PMID 41048107, 2025).
tumor (continued). "Furthermore, IL-15 not only improves the survival and functional capacity of NK cells but also significantly enhances their anti-tumor activity." (PMID 40391220, 2025). "Future strategies may include incorporating NK cell-activating adjuvants, modulating cytokine signaling pathways like IL-15, and using engineered DCs with improved capacity for NK cell engagement to amplify anti-tumor immunity." (PMID 40497988, 2025). "We then investigated whether IL15‐secreted Sell(hi) neutrophils could directly induce the pStat5 Tpex and affected tumor killing T‐cell activity in co‐cultures of OVA‐tumor‐activated OT‐I CD8 T cells (1:1 ratio; 48 h) under C‐P treatments." (PMID 40936164, 2025). "Moreover, stimulation of Vδ1 T cells with IL-2 or IL-15 in vitro induces NKp30 and NKp44, augmenting Vδ1 anti-tumor activity against various leukemias." (PMID 40148988, 2025). "A previous strategy was used because of the dual nature of Vδ1 T cells (Vδ1 T cells expressing high FITC anti‐human amphiregulin (AREG) levels promote tumor proliferation), which included secondary stimulation and induction with IL‐15/IL‐18 to achieve similar results." (PMID 40112194, 2025). "We hypothesize that CD8 T cells are being heavily recruited from the draining lymph nodes into the tumor 48 h after treatment with IL-15 complexes." (PMID 41373645, 2025). "Therefore, combining treatments that can prime anti‐tumor immunity with IL15‐based therapy is crucial to achieve a synergistic impact, particularly for immune “cold” tumors." (PMID 39625860, 2025). "Interestingly, these anti-mesothelin CAR γδ T cells perform even better when IL-15 expression is increased, leading to profound anti-tumor effects both in vitro and in vivo." (PMID 40148988, 2025). "Notably, tumor targeting was achieved and shown relevant for the treatment efficacy of bifunctional antibody-fusion proteins with all three cytokines (IL-15, IL-21 and IL-7) in immunocompetent mouse models." (PMID 40370435, 2025). "Furthermore, the disparate effects of IL15 and IL15c on 4T1 cell proliferation and tumor growth in immunocompromised mice hinted at the existence of a receptor on 4T1 cells selectively recognizing IL15 rather than IL15c." (PMID 39625860, 2025). "However, the early cytotoxicity towards tumor cells in the IL-15 NK cell group also resulted in early drops in cytotoxic population and exhaustion." (PMID 40027823, 2025). "On the contrary, we detected a significant increase in several key Th1 cytokines including IFN-γ, IL-2, and IL-15 by the triple treatment, and all of them are crucial for anti-tumor immunity by enhancing the activity of cytotoxic T cells and natural killer cells." (PMID 40104170, 2025). "GD2.CAR-NKT cells have low persistence, but the inclusion of IL15 in the construct may address this problem and enhance tumor infiltration and antitumor activity in vivo." (PMID 38558810, 2024). "Importantly, memory-phenotype PTPN22-deficient CD8+ T cells, polarized in vitro in the presence of IL-15, had the capacity to clear tumours and were retained in mice for months after tumours became undetectable." (PMID 38334623, 2024). "However, over time these CAR+IL-15-NK cells still lost their anti-tumour functions against highly metabolic tumours, suggested to be due to local depletion of nutrients by the tumours." (PMID 38223411, 2024). "However, repetitive exposure to IL-15 during cancer treatment can diminish viable cell cycle signaling, decreased tumor control, and reduced fatty acid oxidation, resulting in NK cell exhaustion." (PMID 38533507, 2024). "Targeting cytokines such as IL-4, IL-17, IL-15, IL-2 and IL-6 could be an alternative way to create an inflamed tumor microenvironment." (PMID 38928238, 2024). "In line with IL-2, IL-15 stimulates the proliferation of T and NK cells and could be used as anti-tumour drug with successful anti-tumour effects." (PMID 39315059, 2024).
tumor (continued). "The absence of a statistically significant difference in IL-15 levels between the smoking HNC group and the control group, as observed in our study, may serve as an unfavorable prognostic indicator given the critical role of IL-15 in combating tumor growth." (PMID 38672104, 2024). "The differential effects of intracellular and extracellular IL-15 on the cellular behaviors of tumor cells might be related to their mechanisms of action." (PMID 38637902, 2024). "Next, to determine whether the AKT-mTORC1 pathway is involved in the IL-15-induced migration of tumor cells, we used the inhibitors LY294002 and rapamycin to inhibit AKT and mTORC1 activity, respectively." (PMID 38637902, 2024). "However, in a mouse model of breast cancer, IL-15Rα+TAM releases IL-15Rc (the IL-15/IL-15Rα complex) to reduce the expression of chemokine CX3CL1 in tumor cells, thereby reducing recruitment to CD8+T cells." (PMID 38279145, 2024). "Overexpression of IL-15 upregulated the expression of vimentin, a biomarker of mesenchymal-phenotype tumor cells, but did not affect the expression of E-cadherin, a biomarker of epithelial-phenotype tumor cells." (PMID 38637902, 2024). "Pretreatment of NK cells with a combination of Interleukins-15 (IL-15) and IL-18 prior to cryopreservation improves NK cell recovery to ~90-100% and enables equal tumour control in a xenograft model of disseminated Raji cell lymphoma compared to non-cryopreserved NK cells." (PMID 38729924, 2024). "Overall, the data support our development rationale and indicate that GT-00AxIL15 has great potential as a next-generation tumor-targeted IL-15-based immunocytokine both as monotherapy and as combination partner for other cancer therapeutics in a broad range of solid tumor indications." (PMID 38338686, 2024). "Importantly, when mice who had cleared the initial AML graft were rechallenged with tumor cells after 40 days, while in the presence of daily IL-15 administration, CAR T-cells demonstrated ongoing persistence and cytotoxicity." (PMID 39199554, 2024). "Besides IL-15, a more upstream target can be nuclear receptor subfamily 4 group A member 2, which is upregulated in microglia contributing to a pro-tumorigenic tumour microenvironment in glioblastoma." (PMID 38212785, 2024). "We next examined whether IL-15 induces morphological changes in tumor cells via cytoskeletal remodeling." (PMID 38637902, 2024). "Similarly, immunofluorescence staining in tumoural liver 2 weeks after intraportal injection of KPC cells in wild-type mice indicated that CCL3, CCL4 and CCL5, and IL-12, IL-15 and IL-18 are most prominently produced by KCs present at the tumour margin." (PMID 38326607, 2024). "Interestingly, CD70-CAR NK cells demonstrated to be highly competent in eliminating both CD70+ tumor cells and CAFs when stimulated with interleukin (IL)-15." (PMID 38331849, 2024). "The secretion of IL-15 provided greater protection against tumor rechallenge." (PMID 39835140, 2024). "Moreover, using CD40- and FcγR-humanized C57BL/6J mice harbouring MB49 or UPPL1541 tumours, it was shown that the human anti-CD40 agonist antibody 2141-V11 caused reduced tumour size and that this effect was enhanced by cotreatment with IL-15 [37▪]." (PMID 38630912, 2024). "One study showed that incorporation of IL-15 into a NK:CAR product could overcome loss of metabolic fitness, a driver of tumor resistance." (PMID 38690288, 2024). "Immunofluorescence staining confirmed that the expression of chemokines CCL3, CCL4 and CCL5 and the cytokines IL-12, IL-15 and IL-18 by KCs in the liver of Clec4fcreId3f/f mice was reduced or abolished at the tumour margin and in the tumour in comparison to in the littermate controls." (PMID 38326607, 2024). "Various forms of IL-15 may work better when combined with other immunotherapies, although they are effective in inducing tumor regression as a standalone therapy." (PMID 39507777, 2024).
tumor (continued). "Intermittent “spikes” in catecholamines and other acute exercise factors, such as the muscle-derived cytokines IL6 and IL15, can recruit effector lymphocytes to the blood and facilitate their trafficking to tumors leading to enhanced tumor infiltration and suppression of tumor growth over time." (PMID 38592213, 2024). "In addition to the prolonged anti-tumor reactivity by NK:BOB1-TCR/IL-15 in vivo, we observed in one out of four experiments an accumulation of NK:BOB1-TCR/IL-15 cells in several organs of treated mice, leading to death 30 days post NK infusion." (PMID 38690288, 2024). "Finally, NK cells derived from healthy donors and NB patients that were ex vivo stimulated with IL-2 and/or 562-mbIL21 stimulatory cells were injected into NB murine models, along with anti-GD2 and/or IL-2, and IL-15 before and after tumor resection." (PMID 39294470, 2024). "To assess whether Id2 is necessary for the maintenance of stem-like CD8+ T cells, we adoptively transferred IL-15-primed OT-I CD8+ T cells into B16-OVA tumor-bearing B6.SJL mice and investigated the properties of OT-I CD8+ T cells in tumors and tdLNs." (PMID 38287103, 2024). "Thus, high levels of IL-15 expressed by tumor cells improve the responsiveness of tumors to PD-1/PD-L1 blockade-based immunotherapies." (PMID 38637902, 2024). "In nonclinical models, IL15 co-expression in CAR T cells significantly improves their ability to expand, persist, and induce complete tumor regression; however, it is unknown how IL15 impacts CAR T cell antitumor activity and safety in humans." (PMID 38645165, 2024). "Similar effects were also observed in a mouse model of metastatic triple-negative breast cancer (an aggressive, hormone-insensitive carcinoma) treated with heterodimeric IL-15, which lowered the number of tumor cells in the blood and initiated a decline in tumor colonization of the lungs." (PMID 38928185, 2024). "To determine whether endogenous IL-15 in tumor cells affects metastasis in vivo, we used well-established intravenous injection models of lung metastasis in mice." (PMID 38637902, 2024). "Overexpression of both IL-15 and IL-21 has been shown to further enhance anti-tumor effect." (PMID 39039086, 2024). "Potential enhancements to improve CAR‐T cell efficacy for solid tumours include incorporating cytokine support (e.g., IL‐15 or IL‐12) to enhance survival, developing dual or multi‐antigen targeting to prevent tumour escape, and using CRISPR/Cas9 technology to knock out inhibitory receptors." (PMID 39548594, 2024). "Reduced muscle quality will produce less IL-15, affecting the development and survival of natural killer cells, and may ultimately mediate tumor cell immune escape." (PMID 38690276, 2024). "It is interesting to note here that IL-15 has similar functions to IL-2 in that it can stimulate the activation of T-cells, the generation of cytotoxic effector T-cells, and the activation of NK cells, all of which can reduce tumor growth." (PMID 39451257, 2024). "Additionally, replacing IL-2 with IL-7 and IL-15 in the culture media showed beneficial effects for the long-term survival and anti-tumor function of UCAR-T cells." (PMID 39906740, 2024). "However, when exogenous IL-15 engaged tumor cells, a complex containing the IL-15Rα, IL-2/IL-15Rβ, and IL-2Rγ chains was formed, indicating that the differential actions of intracellular and extracellular IL-15 on tumor cells might be caused by their distinctive modes of IL-15 receptor engagement." (PMID 38637902, 2024). "As IL-15 promotes the proliferation of NK cells and T cells, we determined whether cancer cell-intrinsic IL-15 increases the proliferation of tumor cells." (PMID 38637902, 2024). "Interestingly, the level of IL-15 expression in tumor cells was significantly greater in the responding tumors than in the nonresponsive tumors." (PMID 38637902, 2024).
tumor (continued). "Notably, IL‐15 stimulation combined with TIGIT blockade reinvigorates CD8+ TIL‐mediated antitumour immunity in tumour‐bearing mice and LUAD organoids." (PMID 38279870, 2024). "When IL-15 and anti-PD-1 antibodies are combined, they slow tumor growth because of CD8+ T cells." (PMID 39507777, 2024). "However, IL-15 at 6 months post-allogeneic stem cell transplantation returned to pre-transplantation levels, correlating with decreased expansion of anti-tumor NK cell receptors NKp30, NKp46, and NKG2D." (PMID 39200272, 2024). "HepG2 and PLC/PRF/5 HCC tumour cells were incubated with the indicated concentrations of avelumab or cetuximab as indicated prior to co-culture with healthy donor NK cells that had been primed overnight with 1 ng/mL IL-15." (PMID 39286025, 2024). "Recent approaches involve targeted delivery of IL-15 to T cells that may be enriched for antigen specificity capable of mediating anti-tumor immunity, thereby enhancing the therapeutic benefit of IL-15 based therapies." (PMID 38887559, 2024). "This implies that CAR-T cells that secrete IL-15 could potentially boost the efficacy of tumor-cell eradication." (PMID 38402232, 2024). "Additionally, conducting trials to explore the synergistic effects of NK cell therapy with cytokines (e.g., IL-2, IL-15) or other immune stimulants to boost NK cell activity and sustain anti-tumor responses will provide beneficial outcomes." (PMID 39161385, 2024). "This extracellular IL-15 also inhibited tumor cell invasion and motility." (PMID 38637902, 2024). "Finally, fourth-generation CARs consist of engineered cells to self-produce cytokines such as IL-2, IL-15, or IL-12, thereby enhancing their proliferation, migration, and activation towards tumor cells." (PMID 39339180, 2024). "In contrast, NK:BOB1-TCR/IL-15 cells significantly controlled tumor outgrowth in this experiment." (PMID 38690288, 2024). "We show that specified intratumoral doses of CD45-targeted IL-15 and IL-12 are retained at the tumor and TDLNs for prolonged periods of time, leading to extended pSTAT5 signaling and acquisition of a potent effector program by tumor-reactive CD8+ T cells." (PMID 39112631, 2024). "The Tang group utilized biocompatible polymers PEG to mask IL-15 through chemical linkers that are responsive to tumor-specific stimuli, such as high reducing potential and acid pH, which led to equivalent antitumor efficacy to the parental cytokine with markedly reduced toxicities." (PMID 39664443, 2024). "Furthermore, adding an IL-15 cytokine cassette to the mRNA CAR construct drastically improved CD70+ tumor and CAF cell killing in both basic and advanced models." (PMID 38331849, 2024). "Our data indicate that the highly expressed IL-15 in tumor cells may participate in the antitumor immune response in vivo." (PMID 38637902, 2024). "Studies have shown that IL-2 and IL-15 induce the expression of CD107a (degranulation marker) on γδ T cells and give these cells their tumor cell-killing ability and that exogenous IL-2 and IL-15 also enhance the effector functions (especially degranulation/cytotoxic potential) of γδ T cells." (PMID 38515134, 2024). "Interestingly, IL-15, IL-18, and IL-1β cytokine profiles reveal a significant host serum increase after day 35 when the tumor began to progress in growth (respectively)." (PMID 39451257, 2024). "Additionally, compared with control treatment, knockdown of IL-15 reduced but overexpression of IL-15 increased the motility of tumor cells." (PMID 38637902, 2024). "In particular, TREM2+ macrophages can prevent the recruitment and activation of NK cells by blocking the activities of IL-18 and IL-15 through the production of IL-18 binding protein and by inhibiting the production of IL-15 by tumor-infiltrating dendritic cells." (PMID 38426089, 2024). "We next sought to determine whether this enhanced responsiveness to IL-15 signals and capacity for proliferation would translate to superior tumor control." (PMID 38805302, 2024).